SIPA1 (signal-induced proliferation-associated 1)
Diseases named in the same sentence as SIPA1 in open-access papers (continued):
Sharing a sentence is not in itself a finding about the gene and the disease.
breast carcinoma (continued). "Increased primary breast tumour size was also reported in the previous mouse model study, which indicates that it is valuable to examine the possibility of a role for the SIPA1 gene in the initial stage of breast carcinoma in humans." (PMID 19765277, 2009). "Further research, however, is clearly needed to fully explore the role of Rrp1b and Sipa1 in human breast cancer and other tumor types." (PMID 18081427, 2007). "Moreover, SIPA1 was shown to alter glucose metabolism, leading to breast cancer progression, and to aggravate the malignancy of breast cancer by enhancing MYH9 in extracellular vesicles." (PMID 37500797, 2023). "It was shown that SIPA1 overexpression could enhance breast cancer stemness, alter breast cancer metabolism, and enhance breast cancer drug resistance, thereby promoting breast cancer progression." (PMID 37500797, 2023). "Based on these findings, it is most likely that SIPA1 might be a promising drug target for breast cancer and the present study provides a preclinical basis for the development of inhibitors of breast cancer cell metastasis." (PMID 37500797, 2023). "In addition, compared to orthotopic breast cancer samples and healthy breast samples from GEO datasets, the proportion of SIPA1-positive cells in metastatic TNBC cells was higher than that of those cells." (PMID 37500797, 2023). "SIPA1 was detected in the nuclei in multiple breast cancer samples." (PMID 37500797, 2023). "Finally, scRNA-seq of TNBC patient samples indicated a correlation between SIPA1 expression and breast cancer progression." (PMID 37500797, 2023). "We examined the expression and localization of SIPA1 in clinical samples by immunohistochemical staining and H&E staining to determine whether SIPA1 was located in the nuclei in the breast cancer." (PMID 37500797, 2023). "To examine the effect of EVs derived from SIPA1-expressing breast cancer cells on the infiltration of macrophages in vivo, we employed an animal model based on MDA-MB-231 orthotopic mice and treated mice with 231-EVs (n = 6), 231/si-EVs (n = 6), or PBS (n = 6) as control." (PMID 35453742, 2022). "Furthermore, animal models revealed that EVs secreted by breast cancer cells with a high level of SIPA1 expression recruited more macrophages into tumour tissues and promoted metastasis of tumour cells to the lung tissues." (PMID 35453742, 2022). "It suggests that macrophages in breast cancer may be an important factor leading to the decreased RFS of breast cancer patients with high expression of SIPA1 and MYH9." (PMID 35453742, 2022). "However, other ways of regulating the metastasis of breast cancer cells by SIPA1 remain to be explored." (PMID 36230738, 2022). "We next showed that EVs derived from highly metastatic breast cancer cells induced macrophage migration in vitro and that the level of SIPA1 expression in breast cancer cells may influence the components of EVs and the migration of macrophages." (PMID 35453742, 2022). "SIPA1 expression in metastatic tumor tissues was significantly upregulated than that in orthotopic tumor tissues, suggesting SIPA1 might be correlated with breast cancer metastasis." (PMID 36230738, 2022). "In addition, we also found a positive correlation between mRNA levels of MYH9 and SIPA1 genes in breast cancer." (PMID 35453742, 2022). "SIPA1 is distributed in nuclei of breast cancer cell line MDA-MB-231." (PMID 35431649, 2022). "SIPA1 is ectopically localised in the nucleus in some breast cancer cells and could regulate the expression of certain genes, leading to the promotion of cancer cell metastasis." (PMID 35453742, 2022). "To understand whether SIPA1 can promote breast cancer cell metastasis by regulating the lncRNA expression in breast cancer cells, we performed high-throughput sequencing on MDA-MB-231 cells and MDA-MB-231 cells with stable knockdown of SIPA1." (PMID 36230738, 2022).
breast carcinoma (continued). "In this study, we investigated whether breast cancer cells with high SIPA1 expression recruited macrophages into the tumour microenvironment." (PMID 35453742, 2022). "Suggesting that SIPA1 may regulate breast cancer cell metastasis by regulating the expression of this lncRNA and then the EMT process." (PMID 36230738, 2022). "Recent studies have reported that SIPA1 locates in the nucleus of breast cancer cells, and could interact with the promoter of genes, such as ITGB1, CD44, and EPAS1, and upregulate their transcription." (PMID 35453742, 2022). "The results showed that SIPA1 was significantly upregulated in breast cancer tissues." (PMID 36230738, 2022). "Other research showed that lncRNAs can regulate tumor cell metastasis, but the mechanism of whether SIPA1 can regulate lncRNA to promote metastasis of breast cancer cells remains unclear." (PMID 36230738, 2022). "Further cell function experiments proved that knockdown of SIPA1 expression could reduce the adhesion, migration, and invasion of breast cancer cells." (PMID 36230738, 2022). "The quantitative analysis of the average fluorescence intensity of SIPA1 and the ratio of CD68-positive cells in the tumour milieu revealed that the expression level of SIPA1 in breast cancer positively correlated with the ratio of infiltrated macrophages in invasive ductal carcinoma samples." (PMID 35453742, 2022). "We next established stable HIF-2α knockdown MDA-MB-231 cell lines to address the hypothesis that the increased dependence of SIPA1-overexpressing breast cancer cells on aerobic glycolysis was mediated by HIF-2α." (PMID 35096814, 2021). "Taken together, SIPA1 might be a modulator of aerobic glycolysis under normoxia in breast cancer cells." (PMID 35096814, 2021). "The effect of the HGF/MET signaling pathway on breast cancer cells requires the presence of SIPA1." (PMID 33917539, 2021). "Since LDHA is a critical enzyme for the conversion of pyruvate to lactate at the final step of aerobic glycolysis, we set out to determine whether LDH activity was modulated by SIPA1 in breast cancer cells." (PMID 35096814, 2021). "Our previous studies revealed that a high level of SIPA1 expression could promote the metastasis of breast cancer cells." (PMID 32193333, 2020). "Finally, the localization of endogenous SIPA1 was examined by nuclear fractionations and human breast cancer tissue microarrays (TMAs) available through the Human Protein Atlas." (PMID 24260471, 2013). "Experimental manipulation of cellular Sipa1 mRNA levels in a highly metastatic mouse mammary tumor cell line showed that subtle differences in Sipa1 levels significantly affected the ability of the cells to colonize to the lungs, while not impacting primary tumor kinetics." (PMID 22295248, 2012). "We hypothesized that SIPA1 may also be correlated to breast carcinoma incidence as well as prognosis." (PMID 19765277, 2009). "This indicates that SIPA1 transcription at the genetic, expression and protein level may play an integral role in breast carcinoma and represent a key factor in the evolution of this disease." (PMID 19765277, 2009). "The SIPA1 protein has been related to increased breast cancer metastasis in the mouse model." (PMID 19765277, 2009). "The aim of this study is to determine whether SIPA1 (MIM# 602180) plays a similar role in the modulation of metastatic potential in human breast cancer populations." (PMID 16563182, 2006). "Specifically, we report a number of particularly interesting findings regarding nodal status at the time of diagnosis and tumor sex hormone receptor status; these findings suggest that SIPA1 germline variation contributes to metastatic potential in breast cancer." (PMID 16563182, 2006). "Furthermore, these data indicated that the metastatic capacity of mammary tumors in spontaneous metastasis assays was significantly altered by modulation of Sipa1 expression." (PMID 16563182, 2006).
breast carcinoma (continued). "In this study, overexpressed SIPA1 was found in breast cancer tissues by pan-cancer analysis, and the migration assay and fluorescence quantitative PCR assay were used to verify that the SIPA1 protein could promote the EMT process of breast cancer cells to regulate metastasis." (PMID 36230738, 2022). "Indicating the occurrence and development of breast cancer could be blamed for overexpressed SIPA1." (PMID 36230738, 2022). "Taken together, aberrant expression of SIPA1 resulted in the alteration of glucose metabolism from oxidative phosphorylation to aerobic glycolysis even at ambient oxygen levels, which might aggravate the malignancy of breast cancer cells." (PMID 35096814, 2021). "SIPA1 knockdown led to down-regulation of nearly all glycolysis-related genes and increased dependence on respiration, instead of glycolysis, in the generation of ATP, suggesting that the network for glycolytic flux in breast cancer cells could be modulated by SIPA1." (PMID 35096814, 2021). "Taken together, the Sipa1 mRNA expression might be inversely correlated with the methylation status of the CpG island in the Sipa1 promoter-proximal elements of cancer cells, especially in breast cancer cells." (PMID 32193333, 2020). "Taken together, hypomethylation of the CpG island in Sipa1 promoter-proximal elements could enhance SIPA1 expression in breast cancer cells, which could facilitate EMT of cancer cells, possibly increasing a risk of cancer cell metastasis in individuals treated with 5-Aza-CdR." (PMID 32193333, 2020). "To test this hypothesis, we designed a case-only association study in which a number of single nucleotide polymorphisms (SNPs) in SIPA1 were characterized in patients with metastatic or nonmetastatic breast cancer." (PMID 16563182, 2006). "In the present study, SIPA1, a Rap GAP, was identified as a dual-function protein and serves as a transcription factor that promotes the progression of breast cancer." (PMID 37500797, 2023). "To further verify that SIPA1 promotes the malignancy of breast cancer by inducing LINC01615 expression, we knocked down SIPA1 in BT549 and MDA-MB-231 cells and simultaneously overexpressed LINC01615." (PMID 36230738, 2022). "By promoting the expression of integrin 1 by acting on its promoter, SIPA1 further activates the phosphorylation of FAK, and thus regulates invasiveness and morphology of breast cancer cells through the MMP9 signaling and F-actin, respectively." (PMID 35431649, 2022). "Taken together, SIPA1 induced MYH9 transcription and up-regulated its expression at the protein level in breast cancer cells." (PMID 35453742, 2022). "It is thus likely that SIPA1 directly interacted with the EPAS1 promoter, enhanced its promoter activity and promoted HIF-2α expression in breast cancer cells." (PMID 35096814, 2021). "Since overexpressing SIPA1 in breast cancer cell lines increased glucose consumption and lactate production, but decreased ATP production, it is likely that there might exist a SIPA1-induced energy production switch from respiration to fermentation in breast cancer cells." (PMID 35096814, 2021). "Taken together, the present study revealed a novel regulatory mechanism how breast cancer cells, especially TNBC cells highly expressing SIPA1, facilitated cancer progression via a metabolic shift from respiration to aerobic glycolysis." (PMID 35096814, 2021). "We then examined the relationship between SIPA1 protein expression and EMT in breast cancer cell lines." (PMID 32193333, 2020). "Previous studies confirmed that upregulated SIPA1 in breast cancer cell lines, SIPA1 activates the promoter activity of ITGB1 through transcription, which improves the adhesion ability of breast cancer cells, thereby improving the malignancy of breast cancer cells." (PMID 36230738, 2022). "Furthermore, we found that, in breast cancer, the expression of three typical markers of TAMs (CD86, CSF1R, and CCR2) were positively correlated with SIPA1 and MYH9, respectively." (PMID 35453742, 2022).
breast carcinoma (continued). "The SIPA1/HIF-2α axis shifted the ATP source from conventional oxidative phosphorylation to aerobic glycolysis, even in the presence of functional mitochondria, and promoted breast cancer invasion and metastasis both in vitro and in vivo." (PMID 35096814, 2021). "Animal models further showed that the SIPA1/HIF-2α axis could play an important role in aerobic glycolysis and metastasis of breast cancer cells in vivo." (PMID 35096814, 2021). "In order to elucidate the pathway by which SIPA1 modulates the expression of glycolysis-related genes and PDK1, we analyzed RNA-seq data from two pairs of breast cancer cell lines: parental and SIPA1-knowndown MDA-MB-231 cells and parental and SIPA1-overexpressing MCF7 cells." (PMID 35096814, 2021). "SIPA1 is, however, not always highly expressed in all breast cancer cells and other malignant cells, e.g. only a low level of SIPA1 is expressed in the breast cancer cell line MCF7." (PMID 32193333, 2020). "Taken together, SIPA1/HIF-2α axis could be a key regulator of aerobic glycolysis, contributing to the switch from oxidative phosphorylation to aerobic glycolysis in breast cancer cells under an ambient oxygen condition, leading to tumor invasion and metastasis." (PMID 35096814, 2021). "It is, however, not clear whether SIPA1 could regulate or alter the metabolism in breast cancer cells." (PMID 35096814, 2021). "In addition, there was no alteration in the migration activity, confirming that 5-Aza-CdR had no direct effect on the expression of VIM and CDH1 in breast cancer cells with a low level of SIPA1 expression." (PMID 32193333, 2020).
prostate carcinoma (6 papers, 2012 to 2023). A carcinoma that arises from epithelial cells of the prostate gland. "Higher expression levels of SIPA1 were associated with worse prognosis and increased incidence of metastases for prostate cancer (CaP) patients." (PMID 33917539, 2021). "Meanwhile, overexpression of SIPA1 downregulates Brd4, which further attenuates the binding between prostate cancer cells and ECM." (PMID 35431649, 2022). "In vivo overexpression of SIPA1 enhances tumorigenesis of prostate cancer in SCID mice by inhibiting the binding between collagen and fibronectin, thus inactivating ECM-induced activation of Rap1." (PMID 35431649, 2022). "While there has been little research focused on the modulating function of SIPA1 on the regulation of HGF/MET in TJs, previous work from the host laboratory indicated that in breast and prostate cancer cells, the presence of SIPA1 was required for the regulation of HGF/MET in TJs." (PMID 33917539, 2021). "In addition, it is likely that Sipa1 hypomethylation also facilitates the migration of other types of cancer cells, such as colorectal and prostate cancer cells." (PMID 32193333, 2020). "Knockdown of SIPA1 silenced the effect of HGF on TJs in breast and prostate cancer cells." (PMID 33917539, 2021).
melanoma (3 papers, 2012 to 2021). A malignant, usually aggressive tumor composed of atypical, neoplastic melanocytes. "SIPA1 protein overexpression in fast-growing melanoma cell models was confirmed in vitro and in vivo." (PMID 22535842, 2012). "Genes deregulated at the DNA and mRNA level included well-known cancer genes partly already linked to melanoma (RAS genes, PTEN, AURKA, MAPK inhibitors Sprouty/Spred), but also novel candidates like SIPA1 (a Rap1GAP)." (PMID 22535842, 2012). "Accordingly, siRNA-mediated down-regulation of SIPA1 exerted significant effects on clonogenicity, adherence and migration in aggressive melanoma models." (PMID 22535842, 2012). "siRNA-mediated gene knock-down resulted in significantly enhanced cell adhesion capacity in the fast-growing SIPA1-positive melanoma cell model VM-1 (“fast”)." (PMID 22535842, 2012). "Furthermore, clonogenic potential and cell migration capacity were reduced by SIPA1 blockade in the aggressive melanoma cell line while VM-28 cells were almost incapable of migrating through the pores of the trans-well chambers within 48 h." (PMID 22535842, 2012). "However, also novel candidates like SIPA1, a Rap1GTPase, were identified as important drivers of melanoma aggressiveness." (PMID 22535842, 2012). "Interestingly, this led to enhanced cell adhesion but reduced clonogenic potential and migration exclusively in the fast-growing melanoma model, suggesting a complex role of the SIPA1/Rap1 axis in regulating melanoma growth and invasion." (PMID 22535842, 2012). "Pathway identification using the Ingenuity Pathway Analysis software revealed several significant pathways involving regulators of GTPases like Rap1 (SIPA1, a RapGAP protein, and RapGEF2), which pointed toward a significant impact of Rap1 deregulation on melanoma model aggressiveness in vivo." (PMID 22535842, 2012). "Moreover, SIPA1 is considered to be involved in many cancer types, including cervical cancer, gastric cancer, lung cancer, and melanoma, suggesting that SIPA1 may have an active role during progression and metastasis of cancer." (PMID 33917539, 2021). "In contrast, no significant impact was detected in the slow-growing, SIPA1-low melanoma model VM-28 (“slow”)." (PMID 22535842, 2012). "The Rap1 regulatory gene SIPA1 (SPA-1) was most distinctly altered at the DNA and mRNA level in our melanoma subgroups but has not been connected to melanoma before." (PMID 22535842, 2012).
myeloid leukemia (3 papers, 2020 to 2025). A clonal proliferation of myeloid cells and their precursors in the bone marrow, peripheral blood, and spleen. "In SIPA-1-deficient mice, constitutive Rap1 activation in hematopoietic progenitors leads to a spectrum of myeloid leukemias and, less frequently, T-cell leukemias." (PMID 41299498, 2025). "SIPA1 knockout mice showed T cell non-responsiveness before bone marrow dysfunction, which eventually leads to the development of delayed myeloid leukemia." (PMID 35431649, 2022).
triple-negative breast carcinoma (3 papers, 2021 to 2023). An invasive breast carcinoma which is negative for expression of estrogen receptor (ER), progesterone receptor (PR), and human epidermal growth factor receptor 2 (HER2). "SIPA1 has been widely studied in triple negative breast cancer (TNBC)." (PMID 37500797, 2023). "Transcription of fibronectin 1, which is crucial for cell junction and migration of triple-negative breast cancer (TNBC) cells, was regulated by SIPA1 in a DBR-dependent manner both in vivo and in vitro." (PMID 37500797, 2023). "In conclusion, our study found that the up-regulation of SIPA1 can promote the expression of LINC01615, and the up-regulation of LINC01615 can promote the expression of MMP9 to promote the migration and invasion of triple-negative breast cancer." (PMID 36230738, 2022).
breast tumor (2 papers, 2009 to 2021). "We then examined the role of SIPA1/HIF-2α-mediated aerobic glycolysis in breast tumor growth and metastasis in vivo." (PMID 35096814, 2021).
invasive breast ductal carcinoma (2 papers, 2022). "Here, we found that the number of infiltrated macrophages was positively correlated with the expression of signal-induced proliferation-associated 1 (SIPA1) in invasive breast ductal carcinoma tissues and MDA-MB-231 xenograft tumours." (PMID 35453742, 2022).